IL1B (interleukin 1 beta)
Diseases named in the same sentence as IL1B in open-access papers (continued):
Sharing a sentence is not in itself a finding about the gene and the disease.
Hypertension (continued). "Experiments showed that the expression of IL-1β in the PVN region of spontaneously hypertensive rats was elevated, and the expression of anti-inflammatory cytokine IL-10 decreased, indicating that hypertension is accompanied by inflammation." (PMID 33746706, 2021). "PVAT-derived inflammatory cytokines such as TNF-α, MCP-1 and IL-1β impair PVAT anticontractile properties and vascular function in hypertension." (PMID 34409079, 2021). "IL-1β stimulates the expression of vascular cell adhesion protein-1 (VCAM-1), intercellular adhesion molecule 1 (ICAM-1), and E-selectin in essential hypertension patients, which, in turn, results in unwanted atherosclerotic effects." (PMID 33494430, 2021). "IL-1β and IL-18 are products of activated NLRP3 inflammasome; therefore, its role in the development of hypertension was investigated." (PMID 32650532, 2020). "It has been reported that high-salt-induced hypertension activates the sympathetic nervous system through nuclear factor-κB (NF-κB) and increased NLRP3 and IL-1β." (PMID 33633569, 2020). "In a murine model of hypertension, a highly selective SGK1 inhibitor, EMD638683, was shown to suppress IL-1β release, NLRP3 expression, and caspase-1 activation which was associated by reduced transformation of fibroblasts to myofibroblasts." (PMID 32596261, 2020). "Previous studies have reported that proinflammatory cytokines, IL-1β and IL-18, downstream targets of NLRP3 inflammasome, participate in the pathophysiology of cardiovascular disease and hypertension." (PMID 30906225, 2019). "Previous studies suggest that pro-inflammatory cytokines (PICs) such as TNF-α and IL-1β were increased within the PVN of spontaneous hypertensive rats, and lead to the development of hypertension symptoms." (PMID 31708733, 2019). "To test the effect of 8 weeks of aerobic ExT or PVN infusion of TLR4 inhibitor in hypertension, we respectively examined the PVN levels of TNF-α and IL-1β mRNA and protein by RT-qPCR, western blotting, and immunofluorescence staining." (PMID 31708733, 2019). "Within the PVN, TNF-α and IL-1β increased renal sympathetic nerve activity and blood pressure while chronic blockade of TNF-α and NF-κB inhibited hypertension-induced cardiovascular effects." (PMID 24788542, 2014). "Hypertension induced by IP infusion of LPS was accompanied by an increase in plasma levels of CRP, TNFα, and IL-1β, detected on day 7 or 14 after infusion of the endotoxin." (PMID 22958438, 2012). "Intraperitoneal infusion of LPS (1.2 mg/kg/day) for 14 days promoted sustained hypertension and induced a significant increase in plasma level of C-reactive protein, tumor necrosis factor-α (TNF-α), or interleukin-1β (IL-1β)." (PMID 22958438, 2012). "IL-1β (a pro-inflammatory cytokine), MCP-1 (a chemo-attractant cytokine), and VCAM-1 (an adhesion molecule) have been particularly highlighted in the context of endothelial cell dysfunction and hypertension." (PMID 40284196, 2025). "We also detected a significant difference in salivary IL-1β concentrations between patients with and without hypertension, with higher levels in those with the condition (p = 0.010)." (PMID 40572711, 2025). "Previous studies have demonstrated that the renin-angiotensin system (RAS)-mediated hypertension is abolished in rats lacking a functional gene for IL-1β." (PMID 39171117, 2024). "Hypertension-mediated vascular damage at the BBB may allow proinflammatory molecules such as TNF-α, IL-1β to enter the brain and activate glial cells thereby facilitating neuronal cell death." (PMID 38290839, 2024). "Furthermore, monocyte-derived derived DCs from hypertensive mice produce increased amounts of ROS, IL-1β, TNF-α, IL-6, and IL-23 to promote hypertension and end-organ damage." (PMID 37266014, 2023).
Hypertension (continued). "αCD3/αCD28-stimulated cells from men with hypertension produced higher concentrations of IL-1β, likely as an indirect response of myeloid cells to primary T-cell responses compared with cells from men without hypertension." (PMID 37901041, 2023). "Inhibition of NF-κB could attenuate the expression levels of NLRP3, and the expression of IL-1β, and reduce oxidative stress in PVN, then improve hypertension." (PMID 36771206, 2023). "Furthermore, similar results were obtained in Dahl Salt-Sensitive (SS) rats during a 5-week HS intake, which led to hypertension, as well as increased mRNA levels of TNF-α, IL-6, and IL-1β." (PMID 37108475, 2023). "Thus, inhibition of IL-1β activity reduces blood pressure in models of DOCA/salt- and angiotensin II-induced hypertension in mice." (PMID 36937865, 2023). "Our in vivo and in vitro results indicated that blocking VCAM-1 can effectively attenuate Ang II-induced hypertension and cardiac remodeling possibly by reducing VLA-4+ macrophage adhesion/migration and generation of IL-1β, IL6 and TNF-ɑ and ROS, as well as activation of multiple signaling pathway." (PMID 36467095, 2022). "These IsoLG-containing immune cells infiltrate the perivascular space and kidneys and secrete pro-inflammatory cytokines including IL-1β and IL-6 from the APCs and IFN-γ and IL-17A from the T cells, resulting in vascular and kidney dysfunction and ensuing hypertension." (PMID 36620210, 2022). "The generalized linear model adjusting for age, gender, and MAP further confirmed the substantial increase in TIFA protein expression and plasma levels of IL-1β and TNF-α in the order of healthy controls, systemic hypertension, idiopathic PAH, and CTD-PAH patients." (PMID 34238983, 2021). "All the pro-inflammatory biomarkers (IL-1β, IL-6, IL-8, and TNF-α) were positively correlated with the clinical parameters at baseline or following completed treatment, except for the PCR in subjects with hypertension." (PMID 34299815, 2021). "Since it is known that hypertension generally raises TNF-α, IL-1β, IL-6, HIF-1α, TGF-β, and VEGF mRNA and/or protein levels, the results obtained in the study may provide a positive prognostic factor for such activity in vivo." (PMID 33652665, 2021). "As hypertension generally raises TNF-α, IL-1β, IL-6, HIF-1α, TGF-β, and VEGF mRNA expression and/or protein levels, the results obtained in the studied model may provide a positive prognostic factor for such activity in vivo." (PMID 33652665, 2021). "Recent reports showed that hypertension development and EMC changes were limited in SHR rats exposed to ischemic conditioning; this phenotype was accompanied by a marked decrease in IL-1β, implying the depressing effects on the ECM was due to the lowered IL-1β." (PMID 34445357, 2021). "While inhibition of IL-1β with canakinumab reduces cardiovascular event rates, the mechanisms are not related to changes in blood pressure or incident hypertension." (PMID 31884854, 2020). "In the colon, however, baicalin treatment counteracts hypertension-associated increases in the expression of Tlr2, TNF-α, IL-1β, and IL-23 but not HMGB1 in the SHRs." (PMID 31719823, 2019). "Moreover, an inflammatory response in hypertension is characterized by a peripheral and central increase in various PICs, in particular, TNF-α and IL-1β." (PMID 25879545, 2015). "To determine the effect of TLR4 blockade within the PVN on inflammatoy response in hypertension, we examined the levels of pro-inflammatory cytokines (PICs), TNF-α and IL-1β mRNA and protein levels in the PVN by real time RT PCR and western immunoblot, respectively." (PMID 25879545, 2015). "Activation of TLR4 leads to downstream release of inflammatory modulators including TNF-α, IL-1β and MCP-1.Moreover, previous studies demonstrated that inflammation plays a crucial role in the pathogenesis of hypertension, and the development and progression of renalfibrosis." (PMID 26556241, 2015).
Hypertension (continued). "T2DM patients withhypertension show significantly decreased levelsof IL-1β and caspase-1compared to patients without hypertension." (PMID 23762057, 2013). "IL-1β inhibition by anakinra, but not canakinumab, was observed to reduce high blood pressure." (PMID 38256155, 2024). "Specifically, it has been demonstrated that IL-1β could upregulate many proinflammatory genes, including IL-6, IL-17 and IFN-γ, resulting in further tissue injury and inflammation related events, like hypertension and myocardial infarction." (PMID 36703963, 2022). "In addition to inhibiting NF-κB, direct inhibiting IL-1β, the central pro-inflammatory cytokine in NLRP3 pathway, also obtained the results of attenuating hypertension by the activation of renin-angiotensin system and the generation of ROS in paraventricular nucleus." (PMID 36204568, 2022). "However, random allocation to canakinumab, a drug that inhibits IL-1β and reduces both IL-6 and hsCRP, did not reduce the development of incident hypertension nor reduce blood pressure at 3, 6, or 12 months." (PMID 31884854, 2020). "Therefore, to investigate whether TLR4 signaling within the PVN contributes to inflammatory response seen in hypertension, we measured the gene and protein expression of TNF-α, IL-1β and iNOS in the PVN tissue." (PMID 25879545, 2015). "Immunofluorescence and western immunoblot analyses revealed that hypertension contributed to the activation of TLR4 and NF-κB, accompanied by significantly enhanced expression of proinflammatory mediators, such as tumor necrosis factor-α (TNF-α), interleukin-1β (IL-1β), and interleukin-18 (IL-18)." (PMID 24223475, 2013). "Moreover, the level of IL-6, instead of IL-1β, decreased in NLRP3-/- mice, which means that NLRP3 is widely involved in diverse inflammatory responses, and anti-NLRP3 treatment would receive further benefits of relieving auto-inflammation in hypertension pathogenesis." (PMID 36204568, 2022). "Moreover, the mRNA expression of IL-1β and IL-6, intercellular/vascular cell adhesion molecules (ICAM, VCAM) and monocyte chemoattractant protein (MCP-1), have been reported to be enhanced in aortas of hypertensive rats, and in cardiac tissue from different rat models of hypertension." (PMID 20462420, 2010). "We performed multivariate binary logistic regression in the groups (outcome variable: hypertension vs. non-hypertension) with variables identified as significantly different: VLDL, triglycerides, CRP, WBC, NLRP3 (serum), and IL-1β B (saliva)." (PMID 40572711, 2025). "VNS has not yet been tested in human hypertension, but has been used in epilepsy and in RA, demonstrating lowering of circulating TNF-α, IL-1-β, and IL-6 levels and improvement in disease activity." (PMID 34698811, 2021). "Subjects who developed hypertension were significantly heavier and had higher systolic and diastolic BP, hs-CRP levels, and IL-1β levels at baseline than did subjects who did not develop hypertension during the mean follow-up of 2 years." (PMID 32292598, 2020). "Interestingly, IL-1β antagonist significantly reduced blood pressure in one kidney/deoxycorticosterone acetate (DOCA)/salt-induced hypertension in rats, despite the fact that monoclonal antibody against IL-1β did not reduce blood pressure or incident hypertension during follow-up in CANTOS." (PMID 33995071, 2021).
gastric cancer (205 papers, 2007 to 2026). A primary or metastatic malignant neoplasm involving the stomach. "IL-1β induces gastric cancer by blocking the production of gastric acid, causing epigenetic changes, stimulating angiogenesis, attracting adhesive factors, and releasing other inflammatory factors, such as interleukin-8 (IL-8/CXCL8)." (PMID 39950099, 2024). "The T allele of IL-1B-511 increases the risk of gastric cancer, especially in the combination of the T allele and virulence markers (cagA positive, vacAs1 and vacAm1)." (PMID 38867324, 2024). "Elevated expression of IL-1β can lead to a decrease in secretion of gastric acid, which is associated with development of gastric cancer." (PMID 38978704, 2024). "Recent research has confirmed that interleukin-1β (IL-1β) is associated with the facilitation of gastric cancer following Helicobacter pylori (HP) infection, and chronic inflammation plays a critical role in the growth and proliferation of GC." (PMID 39950099, 2024). "As a matter of fact, the IL1B-511 T allele has been linked to severe gastric inflammation and gastric cancer within Brazilian and Italian populations." (PMID 36838318, 2023). "Polymorphisms in the IL-1β gene resulting in elevated IL-1β production are associated with an increased risk of gastric cancers and shorter survival in pancreatic cancer patients." (PMID 36742298, 2023). "Protein–protein interaction and co-expression analysis showed a strong association of CXCL1 with CXCR1, CXCR2, IL6, and IL1B in human gastric cancer tissue samples." (PMID 36614235, 2023). "IL-1β is a pro-inflammatory cytokine whose overexpression is closely linked to the development of gastric cancer in H. pylori-infected patients." (PMID 36838318, 2023). "An Asian-Chinese case–control study reported association between IL1B SNP rs1143634 (+ 3954C>T) and gastric cancer risk [co-dominant model: OR [95% CI) = 6.93 (3.13–15.36)]4." (PMID 37147350, 2023). "H. pylori infection triggers the up-regulation of mesenchymal-epithelial transition factor (MET) in exosomes and activates tumor-associated macrophages through IL-1β, thereby promoting gastric cancer progression." (PMID 35795038, 2022). "In patients with genetic polymorphisms such as in the IL-1β gene, IL-1β–511 T and IL-1B-31 C alleles are significantly associated with an increased risk of developing gastric carcinoma." (PMID 35204598, 2022). "The SNP rs16944 C/T in IL1β gene related to the promoter region has been associated with increased IL1β production with a consequent increased risk of developing inflammatory diseases and gastric carcinoma." (PMID 36428884, 2022). "In Chinese population, the individuals carrying the IL-1β-511C/T genotypes (CT carriers) have an increased risk of developing gastric cancer." (PMID 34484153, 2021). "Another well studied pro-inflammatory protein/gene is IL-1β/IL1B; several studies have provided evidence about the association of IL1B-511 (rs16944) with gastric cancer, gastritis risk, including meta-analysis." (PMID 33671828, 2021). "The IL-1β-511T+, IL-1β-31C+, and IL-1RN 2/2 polymorphisms are shown to be associated with the increased risk of hypochlorhydria and gastric cancer." (PMID 34484153, 2021). "IL-1β is a potent pro-inflammatory cytokine expressed in H. pylori infection, and it is related to tumorigenic-associated gastric cancer." (PMID 33498958, 2021). "IL-1β is considered to be a central factor for gastric malignancy, as is supported by evidence that IL-1B gene polymorphism increases the risk of gastric cancer and overexpression of IL-1β leads to gastric inflammation and cancers in mice." (PMID 32582201, 2020). "IL-1β polymorphisms are linked with increased gastric cancer risk in humans, and in mice, IL-1β overexpression induced gastric inflammation and cancer." (PMID 32216812, 2020).
gastric cancer (continued). "This pleiotropic cytokine IL-1β is associated with enhanced metastasis and poor prognosis of gastric cancer and was reported to stimulate the expression of IL-8, another inflammatory cytokine, through mitogen-activated protein (MAP) kinase and ROS signaling." (PMID 32377300, 2020). "Recently, polymorphisms of the IL-1B gene and IL-1 receptor antagonist (IL-1RN) have been revealed to be associated with H. pylori-related gastric cancer in the Chinese, Italian, and Indian population." (PMID 32582201, 2020). "For instance, interleukin (IL)-1β directly induced promoter methylation of CDH1 encoding the tumor suppressor E-cadherin in a mouse model of gastric cancer." (PMID 32678024, 2020). "IL-1β signaling works as an inhibitor of acid secretion and causes gastric atrophy, which provides a hotbed for metaplasia and gastric cancer development." (PMID 32230726, 2020). "For example, IL1B-511 C > T (rs16944) and IL-1β-31 C > T (rs1143627) T alleles are associated with an increase in IL-1β serum concentration in cervical and gastric cancer patients, or in the supernatant of cells harboring rs1143627." (PMID 32635472, 2020). "Interleukin-1β (IL-1β) is implicated in gastric cancer development and certain gene polymorphisms play a role in this scenario." (PMID 32230726, 2020). "In particular, a specific interleukin-1β (IL-1β) gene polymorphism has prominence and was implicated in hypochlorhydria and gastric cancer development." (PMID 32230726, 2020). "In gastric cancer the survival of tumor cells is increased by IL-1β, induced under conditions of tumor-associated inflammation." (PMID 31557902, 2019). "Persistently high levels of IL-1β and IL-18 suppress acid secretion, allow hypoacidity in the stomach, loss of parietal cells, gastric atrophy, metaplasia, and eventually gastric cancer." (PMID 29686666, 2018). "Another significant mechanistic link between IL-1β and an increased risk of gastric cancer is the induction of aberrant DNA methylation via this interleukin." (PMID 30042333, 2018). "H. pylori synergistic with IL-1β gene polymorphisms seem to promote gastric cancer by their involvement in precancerous gastric lesions and hypochlorhydria." (PMID 30123433, 2018). "One of them is IL-1β (rs16944), which in the promoter region has been associated with increased IL-1β production and with increased risk of developing cancers, such as gastric carcinomas and ovarian cancer." (PMID 30211233, 2018). "The aim of this study is to clarify the associations between IL-1B31C/T, IL-1B-511C/T, IL-8-251T/A gene polymorphisms and the risk of Helicobacter pylori (H. pylori) infection together with H. pylori-related gastric cancer (GC), peptic ulcer disease (PUD)." (PMID 28453551, 2017). "Polymorphisms of interleukin-1beta (IL-1β) involved in enhancing production of IL-1β are associated with an increase risk for both hypochlorhydria induced by H. pylori and gastric cancer." (PMID 27713138, 2017). "With this in mind, we conducted the updated meta‐analysis, aiming to provide a quality assessment of the association between IL‐1B 31 polymorphism and gastric cancer risk." (PMID 26805397, 2016). "Nevertheless, we substantiated that IL‐1B 31T conferred genetic susceptibility to gastric cancer among H. pylori infection‐positive individuals." (PMID 26805397, 2016). "In a model of H. felis-associated gastritis and gastric cancer, infected transgenic mice that constitutively over-express IL-1β in parietal cells were shown to develop more severe lesions than infected WT control mice." (PMID 27045955, 2016). "There was evidence of significant between‐study heterogeneity among overall studies of the IL‐1B 31 polymorphism and gastric cancer risk under all the genetic models." (PMID 26805397, 2016). "Overall, this systematic review produced 37 eligible studies, consisting 6108 cases and 8980, for the pooled analysis of the association between IL‐1B 31 polymorphism and gastric cancer risk." (PMID 26805397, 2016).